TWIST1 (twist family bHLH transcription factor 1)
Diseases named in the same sentence as TWIST1 in open-access papers (continued):
Sharing a sentence is not in itself a finding about the gene and the disease.
breast carcinoma (continued). "Consistent with the importance of reversible EMT in TWIST1‐driven metastasis, endogenous SNAIL1 expression was found to be restricted in cells at the invasive fronts of primary tumors and in CTCs, but not within the macrometastatic lesions in multiple genetic mouse models of breast cancer." (PMID 28085222, 2017). "Interestingly, we found that miR-33a and miR-151 are significantly negative correlated with TWIST1 gene expression in breast cancers." (PMID 27930738, 2016). "Moreover, we found that ectopic expression of miR-151-3p by infection with adenoviruses expressing miR-151 significantly decreased TWIST1 expression, migration and invasion, but did not affect cell growth and tumorsphere formation of human breast cancer cells." (PMID 27930738, 2016). "In addition, the protein levels of TRIM28 and TWIST1 are not only elevated but also positively correlated with each other, suggesting that TRIM28 and TWIST1 may play important roles in breast cancer development and/or invasiveness." (PMID 27412325, 2016). "Interestingly, the data obtained from TCGA revealed a significant negative correlation between the TWIST1 mRNA levels and miR-151 expression levels in human breast cancers." (PMID 27930738, 2016). "Thus, miR-129-5p down-regulation fosters EMT in breast cancer by increasing Twist1-Snail and activating a negative feedback loop." (PMID 26460733, 2015). "Because some cancer cells do not have TWIST1/N-cadherin signaling, such as prostatic cancer LNCaP cells or breast cancer MCF-7 cells, we wished to determine whether molecular mechanism of metformin's action in these N-cadherin deficiency cancer cells." (PMID 26359363, 2015). "Moreover, we found that miR-33b does not alter the 3′UTR activity of the well-established EMT transcription factor SNAI2, suggesting that miR-33b regulates HMGA2, SALL4 and Twist1 in breast cancer cells without impacting EMT." (PMID 25919570, 2015). "More importantly, the co-expression of TWIST1 and IL8 is correlated in the basal and ERBB2 subtypes, the two most aggressive subtypes of human breast cancers, supporting the important roles of the transcription factor and the cytokine in the pathology of advanced breast cancers." (PMID 22891766, 2012). "Due to the speed with which SCC developed in the MMTV-Cre;K-rasG12D;Twist1 animals, the role of TWIST1 in promoting mammary tumor formation could not be assessed." (PMID 22654675, 2012). "ARTN and TWIST1 synergize to produce a worse outcome in ER-MC and combined inhibition of ARTN and phosphatidylinositol 3-kinase/protein kinase B (PI3K/AKT) may therefore provide a novel therapeutic strategy in this subtype of mammary carcinoma." (PMID 22060274, 2011). "Depletion of TWIST1 reduced the basal capacity for monolayer proliferation, colony formation in soft agar, 3D matrigel growth and migration and invasion in Transwell assays of BT549-VEC and MDA-MB-23-VEC cells as previously reported for mammary carcinoma cells." (PMID 22060274, 2011). "Furthermore, we demonstrated that circLRBA could interact competitively with the E3 ubiquitin ligase SPOP to hinder the binding between SPOP and Twist1 and enhance the transcriptional activation of PD‐L1, thus promoting the EMT, chemoimmunotherapy resistance and metastasis of breast cancer." (PMID 41082269, 2025). "Moreover, TWIST1 knockdown in several breast cancer cell lines has been reported to downregulate their metastatic abilities, whereas TWIST1 upregulation suppress E-cadherin expression and prime EMT, suggesting that TWIST1 can induce metastasis through promoting EMT." (PMID 36474162, 2022). "Moreover, knockdown of Sox4 reversed the effect of miR-381-3p depletion on breast cancer proliferation and invasion in MCF7 cells, whereas knockdown of Twist1 reversed the effect of miR-381-3p depletion on breast cancer invasion, but not altered the proliferation in MCF7 cells." (PMID 34362391, 2021).
breast carcinoma (continued). "Importantly, we describe for the first time the ability of melatonin to counteract the stimulatory effect of doxorubicin on TWIST1 (Twist-related protein 1) expression and protein levels in estrogen-dependent but not in estrogen-independent breast cancer cells." (PMID 31331001, 2019). "Therefore, we decided to test the effect of doxorubicin and melatonin on the expression of various miRNAs involved in epithelial to mesenchimal transition (EMT), cell growth, migration, invasion, stem cell expansion and breast cancer progression, in correlation or not with TWIST1." (PMID 31331001, 2019). "Besides regulating EMT, Twist1 is also a transcription factor for miR-10b; thus, it can be hypothesized that tumor cells with EMT characteristics may contribute to the increased miR-10b levels in the serum of M1 patients with HER2+ breast cancer." (PMID 24416156, 2014). "We have previously shown that the ectopic expression of TWIST1 alone can effectively reprogram the luminal epithelial, non-metastatic ER+/HER2− MCF7 breast cancer cells into mesenchymal, metastatic ER−/HER2− basal-like breast cancer cells." (PMID 38893094, 2024). "Invasive luminal B breast cancer LCs were reported to express epithelial markers KRT14 and p63 but lacked expression of typical EMT markers TWIST1, Slug, and vimentin." (PMID 39408880, 2024). "Taken together we found that, on the one hand, USP13 stabilizes Twist1 and, on the other hand, Twist1 inhibits USP13 promoter activation, thereby forming a negative feedback loop in breast cancer cells." (PMID 36732432, 2023). "Through expression of twist family BHLH transcription factor 1 (TWIST1), ARTN increases metastasis in patients with estrogen receptor (ER)-negative mammary cancer (ER-MC)." (PMID 36471885, 2022). "Unlike thyroid and breast cancers, we did not identify PDGFRA regulation of TWIST1 or SNAIL expression (data not shown) in GIST, whereas SLUG expression was modulated by PDGFRA activation." (PMID 33603171, 2021). "Immunohistochemistry results showed up-regulation of TWIST1 in breast cancer tissues, and a significantly negative correlation between TFPI2 and TWIST1 in breast cancer was determined via bivariate correlation analysis." (PMID 32248791, 2020). "Initially, we screened various breast cancer cells with and without invasiveness to identify if BTG2 and Twist1 expressions are mutually exclusive." (PMID 31138781, 2019). "The function of PRMT1 in modulating EMT was suggested through the regulation of Zinc Finger E-Box Binding Homeobox 1 (ZEB1) in breast carcinoma and Twist Family BHLH Transcription Factor 1 (TWIST1) in non-small lung carcinoma." (PMID 31655611, 2019). "We compared the expression of TWIST1 and IL8 in multiple breast cancer cell lines, which revealed that both TWIST1 and IL8 are expressed in the basal but not in the non-basal breast cancer cell lines." (PMID 22891766, 2012). "In spite of the fact that in human breast cancer cells, NF-κB binds to the promoter regions of Snai2, Twist1, and ZEB2 and activates their transcription, PDGF-AB does not increase the expression of Snai2, Twist1, and ZEB2 in brain ECs." (PMID 32226439, 2020). "In addition, we compared two breast cancer cell lines: MCF7, a luminal ER-positive cell line that expresses E-cadherin, and MDA-MB-231, a basal-like triple-negative cell line, positive for ZEB1 but not TWIST1 expression." (PMID 39851508, 2025). "Consequently, this ectopic expression of TWIST1 is sufficient to reprogram MCF7 cells, which are non-metastatic luminal epithelial ER+/HER2− breast cancer cells, into metastatic basal-like ER−/HER2− breast cancer cells with mesenchymal gene expression." (PMID 38893094, 2024).
prostate carcinoma (110 papers, 2009 to 2026). A carcinoma that arises from epithelial cells of the prostate gland. "miR-145-5p serves as a significant factor controlling the expression of TWIST1 in prostate cancer and is implicated in the regulation of cytoplasmic polyadenylation element-binding proteins." (PMID 40689207, 2025). "TWIST1 upregulation of SOX2 was associated with the promotion of cancer stem cell-like properties in prostate cancer cells and also with the progression of triple-negative breast cancer." (PMID 39593172, 2024). "Twist1 upregulation has been implicated in bone metastasis of prostate cancer and high Twist1 expression is indicative of poor prognosis." (PMID 32296610, 2020). "We further investigated a panel of mouse prostate cancer cell lines derived from the mouse model, and specifically analyzed the expression pattern of Twist1 due to its association with prostate cancer." (PMID 29455655, 2018). "Our data suggest that miR-145-5p is a major factor in the control of TWIST1 expression in prostate cancer, and that loss of miR-145-5p may constitute a key step in progression toward metastasis." (PMID 33227047, 2020). "Also, ZEB1 expression was associated with prostate cancer (PCa) progression and metastasis, while Twist1 plus ZEB2 expression was related to early disease recurrence in HCC." (PMID 28590039, 2017). "We also show that SKP2 overexpression in prostate cancer PC3 cells increases the protein levels of TWIST1 and the expression of EMT related genes, including FMOD, THY1, NFIL3 and IRF2, leading to a marked increase in migration and invasion." (PMID 41542047, 2026). "In the context of prostate cancer, TWIST1 has been shown to induce the overexpression of the androgen receptor (AR), a critical factor in AGA, thereby potentially increasing the sensitivity of HFs to androgens." (PMID 40565255, 2025). "CLU acts as a downstream mediator of TGF-beta in prostate cancer, which is activated by Twist1 (transcription factor)." (PMID 39253532, 2024). "TWIST1 is highly expressed in prostate cancer, and expression levels are correlated with higher Gleason scores and poor prognosis." (PMID 36674745, 2023). "Numerous studies have shown that ADT can result in an increase in expression of mesenchymal markers such as vimentin, N-cadherin and TWIST1, and a decrease in epithelial markers, especially E-cadherin, in prostate cancer PDX model and patient tumours." (PMID 35493092, 2022). "A complementary prospective study with clinical prostate cancer samples has suggested that miR-145-5p and/or CPEB1 deficiencies are associated with TWIST1-dependent promotion of tumor growth and metastasis." (PMID 33227047, 2020). "Future studies can focus on the importance of Twist1 in mediating other steps of prostate cancer metastasis, including intravascular migration and extravasation and invadopodia formation." (PMID 32296610, 2020). "Collectively, these data strongly argue that ETV1 regulates basal Twist1 expression and, more importantly, mediates the androgen-dependent expression of Twist1 in prostate cancer cells." (PMID 32296610, 2020). "We show that tumor suppressor miR-145-5p controls TWIST1 expression in an immortalized prostate epithelial cell line and in a tumorigenic prostate cancer-derived cell line." (PMID 33227047, 2020). "Consistent with these gene expression changes, Twist1 depletion strongly repressed the migration of prostate cancer cells, comparable in effect to AR knockdown." (PMID 32296610, 2020). "One important gene involved in metastasis is Twist1, which was identified several years ago to be androgen-regulated in prostate cancer." (PMID 32296610, 2020). "Strikingly, the function of miR-145-5p as a TWIST1 regulator was masked in 22Rv1 prostate carcinoma cells, which express high levels of CPEB1." (PMID 33227047, 2020).
prostate carcinoma (continued). "An increase in TWIST1 expression has been documented with respect to prostate cancer progression, since its overexpression correlates with a high Gleason score." (PMID 33227047, 2020). "We have discovered that miR-145-5p mediated control of TWIST1 in human prostate cancer cells is context-dependent, since it relies on the CPEB1 expression level." (PMID 33227047, 2020). "In this study we demonstrate that androgen-activated AR promotes the expression of Twist1 in prostate cancer cells." (PMID 32296610, 2020). "We further show that Twist1 promotes EMT and migration of prostate cancer cells, and our data suggest that Twist1 plays an important role in mediating the AR induction of EMT and cell migration." (PMID 32296610, 2020). "It will be interesting to determine in future work if the AR indirect up-regulation of Twist1 via ETV1 is involved in these other steps of prostate cancer metastasis." (PMID 32296610, 2020). "The mechanisms that trigger aberrant expression and up-regulation of Twist1 in prostate cancer are also poorly understood." (PMID 32296610, 2020). "To conclude, our work provides evidence that miR-145-5p and CPEB1 functionally overlap to control TWIST1 expression in prostate cancer cells by preventing EMT expression, cell migration, and stem cell properties." (PMID 33227047, 2020). "Down-regulation of Twist1 in androgen independent prostate cancer cells increased anticancer drug sensitivity and suppressed cell migration and invasion." (PMID 30973923, 2019). "In prostate cancer, increased expression of TWIST1 plays an important role in the development of prostate cancer which is consistent with our result." (PMID 31060254, 2019). "In our study, we analyzed the association of CDK4, TWIST1, and SNAI2 single gene expression with the prognosis of prostate cancer patients in the GSE21032 dataset taken from the SurvExpress database." (PMID 31060254, 2019). "In summary, we concluded that TWIST1 is negatively associated with ETV6 and is involved in tumor progression in human prostate cancer." (PMID 29455655, 2018). "We further investigated the relationship between ETV6 and TWIST1 in human prostate cancer tissues collected from the Taipei Medical University Joint human biological database (approval no.: 201,311,034, Taipei, Taiwan)." (PMID 29455655, 2018). "On the other hand, high expression of MAOA in human tissues correlates with poor prognostic in prostate cancer patients and increased tumor metastasis in xenograft mouse model of prostate cancer via HIF1-α/VEGF-A/FOXO1/TWIST1 signaling pathway." (PMID 29334991, 2018). "Our results support a novel EGFR-ETV6-TWIST1 pathway in that ETV6 serves as a gatekeeper to maintain TWIST1 at low levels in prostate cancer." (PMID 29455655, 2018). "Twist1 is overexpressed in various types of human cancers including breast, stomach, and prostate cancers, and is a prognostic marker of metastatic prostate cancer." (PMID 28977889, 2017). "In prostate cancer a key role for Twist1 during EGF-induced EMT and tumor invasion has been proposed since it acts as a crucial downstream mediator of these events." (PMID 28430640, 2017). "The results of this study are consistent with previous reports demonstrating that FOXO1 inhibits Twist1 mRNA expression in prostate cancer cells." (PMID 27924058, 2017). "Twist1 has been demonstrated to induce N-cadherin at the mRNA level through the E-box cis-element located within the first intron of the N-cadherin gene in prostate cancer." (PMID 28099910, 2017). "Here, combined RNA-seq and ChIP-seq analysis reveals that REST is involved in epithelial-mesenchymal transition (EMT) and stemness acquisition in NE differentiated prostate cancer (PCa) cells via direct transcriptional repression of Twist1 and CD44." (PMID 28256535, 2017). "Previous studies suggested that Twist1 was a novel factor in the development and progression of many cancers, such as prostate cancer." (PMID 27793033, 2016).
prostate carcinoma (continued). "We have previously shown that ERβ2 increased expression of EMT-associated genes Twist1 and Slug (SNAI2) in prostate cancer cells." (PMID 26010887, 2015). "Here, we show that ERβ2 also increased activity of a luciferase reporter driven by the HIF-1α-dependent Twist1 promoter in LNCaP prostate cancer cells and that this effect was dependent upon the HIF-1α response element." (PMID 26010887, 2015). "For example, in prostate cancer, N-CADHERIN expression was associated with a nuclear translocation of Twist1." (PMID 23658830, 2013). "In support of this, a positive correlation between the level of TWIST1 and prostate cancer metastasis has been reported." (PMID 23368843, 2013). "Our finding that NKX3-1 represses TWIST1 expression emphasizes the functional importance of NKX3-1 in regulating TWIST1 expression during prostate cancer progression to metastatic disease." (PMID 23368843, 2013). "We show that NKX3-1 binds to the TWIST1 promoter and that NKX3-1 over-expression reduces the activity of a TWIST1 promoter reporter construct, whereas NKX3-1 siRNA up-regulates endogenous TWIST1 mRNA in prostate cancer cells." (PMID 23368843, 2013). "In support of this notion, Sham and co-workers reported recently that the up-regulation of the basic-helix-loop-helix factor Twist1 by NF-kB increases chemoresistance of PC3 prostate cancer cells treated with daunorubicin or cisplatin." (PMID 20152043, 2010). "Furthermore, miR-145-5p interacts with lnc-ZNF30-3 in prostate cancer through a ceRNA mechanism: lnc-ZNF30-3 acts as a molecular sponge, sequestering miR-145-5p and negating its inhibitory effects on TWIST1 and other EMT-associated transcription factors." (PMID 40689207, 2025). "Collectively, these data suggest that EV from a proinflammatory environment may exacerbate the malignant phenotype of prostate cancer cells by manipulating the TWIST1/EMT signaling axis and that this axis may serve as a potential therapeutic target." (PMID 36674745, 2023). "TWIST1 acts in concert with other EMT transcription factors including SLUG and SNAIL, and expression of TWIST, SLUG, and SNAIL is associated with poor outcomes in prostate cancer patients." (PMID 36674745, 2023). "Twist1 regulates WDR5-Hottip-mediated Hoxa9 chromatin to promote prostate cancer metastasis." (PMID 36639679, 2023). "STAT3 mediates TGF-β1-induced Twist1 expression leading to prostate cancer invasion." (PMID 35408745, 2022). "Furthermore, a similar effect of TWIST1 on invasion potential has been observed also in other types of tumours, such as prostate cancer, melanoma, and glioblastoma." (PMID 33983406, 2021). "In addition, Twist1 knockdown in androgen-independent prostate cancer cell lines results in decreased cell invasiveness." (PMID 32296610, 2020). "Parallel to all these, TWIST1 expression is upregulated in many types of cancer including glioma, stomach, liver, endometrium, breast, prostate cancer, angiogenesis, and epithelial-mesenchymal transition." (PMID 32922123, 2020). "Twist1 appears to induce EMT in prostate cancer cell lines by repressing E-Cadherin expression." (PMID 32296610, 2020). "However, we discovered that the translational inhibitory effect of miR-145-5p on TWIST1 is lost in 22Rv1, another prostate cancer cell line that intrinsically expresses high levels of the CPEB1 cytoplasmic polyadenylation element binding protein." (PMID 33227047, 2020). "Our data here clearly demonstrate both endogenous and exogenous ETV1 can promote expression of Twist1 in prostate cancer cells, and this ETV1 positive effect was also observed on a Twist1-Luc reporter plasmid, which is a consistent with a direct effect of ETV1 on the Twist1-promoter." (PMID 32296610, 2020).